ABT1 (activator of basal transcription 1)
Description:
Could be a novel TATA-binding protein (TBP) which can function as a basal transcription activator. Can act as a regulator of basal transcription for class II genes (By similarity).
Synonyms: hABT1; Esf2
Tractability: PROTAC: ubiquitination databases record sites on it; its protein half-life has been measured.
Gene: Protein-coding gene on chromosome 6 (26,596,953 to 26,600,739, forward strand). Ensembl gene ENSG00000146109.
Subcellular location: Nucleus; Nucleus, nucleolus
Subcellular location (Human Protein Atlas): Vesicles
Gene Ontology:
Molecular function: protein binding; RNA binding; transcription coactivator activity; nucleic acid binding
Biological process: endonucleolytic cleavage in 5'-ETS of tricistronic rRNA transcript (SSU-rRNA, 5.8S rRNA, LSU-rRNA); endonucleolytic cleavage in ITS1 to separate SSU-rRNA from 5.8S rRNA and LSU-rRNA from tricistronic rRNA transcript (SSU-rRNA, 5.8S rRNA, LSU-rRNA); endonucleolytic cleavage to generate mature 5'-end of SSU-rRNA from (SSU-rRNA, 5.8S rRNA, LSU-rRNA); small-subunit processome assembly; transcription by RNA polymerase II; positive regulation of DNA-templated transcription; regulation of DNA-templated transcription
Cellular component: nucleolus; nucleus; transcription regulator complex
Genetic constraint (gnomAD): Loss-of-function variants: 14 observed, 18.24 expected, observed/expected ratio (o/e) 0.77, 90% interval 0.51 to 1.2. The upper end of that interval is the gene's LOEUF score, 1.2, which puts it in group 5 of 6, group 1 being the genes least tolerant of losing a copy. Missense variants: 425 observed, 395.64 expected, observed/expected ratio (o/e) 1.07, 90% interval 0.99 to 1.16. Synonymous variants: 164 observed, 151.69 expected, observed/expected ratio (o/e) 1.08, 90% interval 0.95 to 1.23.
Homologues: Orthologues: chimpanzee ABT1 (100% identical), macaque ABT1 (97% identical), rabbit ABT1 (89% identical), dog ABT1 (88% identical), guinea pig ABT1 (88% identical), pig ABT1 (86% identical), rat Abt1 (80% identical), mouse Abt1 (78% identical), zebrafish abt1 (48% identical), tropical clawed frog abt1 (33% identical), Drosophila melanogaster CG32708 (25% identical), Caenorhabditis elegans F57B10.8 (25% identical), and 24 more.
Diseases named in the same sentence as ABT1 in open-access papers:
ABT1 is named in the same sentence as 10 diseases in open-access papers, as found by Europe PMC text mining. Sharing a sentence is not in itself a finding about the gene and the disease. The quoted sentences say what the papers report.
sarcoidosis (1 paper, 2025). Sarcoidosis is a multisystemic disorder of unknown cause characterized by the formation of immune granulomas in involved organs. "Among them, there were 14 genes (ABT1, BTN2A2, C2orf74, CCDC88B, FAM213A, MDH2, METTL21B, PRSS16, RP3-473L9.4, TCF19, TSFM, UBASH3A, UQCC2, ZSCAN26) associated with sarcoidosis risk consistently across these tissues." (PMID 40075078, 2025). "In addition, our TWAS pinpointed many tissue-specific sarcoidosis-associated genes and found expressions of 14 genes (ABT1, BTN2A2, C2orf74, CCDC88B, FAM213A, MDH2, METTL21B, PRSS16, RP3-473L9.4, TCF19, TSFM, UBASH3A, UQCC2, ZSCAN26) associated with sarcoidosis across all three target tissues." (PMID 40075078, 2025).
ABT1 also shares sentences with these, for which no sentence is quoted: tumor (3 papers); breast carcinoma (1); cancer (1); depression (1); gastric cancer (1); infection (1); motor neuron disease (1); ovarian serous cystadenocarcinoma (1); renal clear cell carcinoma (1).